IFNG (interferon gamma)
Diseases named in the same sentence as IFNG in open-access papers (continued):
Sharing a sentence is not in itself a finding about the gene and the disease.
tumor (continued). "Interferon-gamma (IFN-γ) released from tumour infiltrating lymphocytes (TILs) induces PD-L1 expression by tumour cells." (PMID 35228677, 2022). "Elegant in vivo imaging revealed that a feedback loop of enhanced intratumoral T cell IFNγ expression stimulated local IL-12 production by dendritic cells (DCs) to then fully drive the CD8 anti-tumor T cell response." (PMID 35472220, 2022). "Similar to Ki67 expression, IFNγ levels in tumours treated with ICB exhibited a slight decrease compared to vehicle tumours." (PMID 36010935, 2022). "M1 polarized macrophages are activated by TNFα and IFNγ and promote pro-inflammatory activity, which supports the cytotoxic potential and possesses anti-tumor functions." (PMID 35736195, 2022). "Interferon-gamma (IFN-γ) secreted by tumor-infiltrating T cells stimulated Gal-9 expression on antigen presenting cells (APCs)." (PMID 36368952, 2022). "Active mature NK cells have critical antiviral and anti-tumor functional roles; however, an NK cell’s switch to a less active and immature phenotype, confirmed by low cytolytic and low IFNγ production, was detected during HBV chronic infection and HBV-HCC." (PMID 35267563, 2022). "IFNγ can inhibit proliferation of tumor cells and even trigger apoptosis by up-regulating molecules that promote apoptosis, for example, caspase-1." (PMID 36271507, 2022). "These dimeric, monospecific aptamers were shown to activate cytotoxic T lymphocytes (CTLs; as measured by increased IFNγ release), prevent tumor growth in vivo, and prolong animal survival in various murine models." (PMID 35141049, 2022). "Tumour microenvironment changes due to IFNγ were observed, and in particular T-cell infiltration and tumour-surface MHC-I expression was reported." (PMID 36686827, 2022). "In a syngeneic mouse renal adenocarcinoma tumor model therapeutic IL-12 induced production of IFNγ by the NK cells led to upregulated TRAIL surface expression on NK cells and substantially suppressed tumor metastasis in lungs and liver." (PMID 36496977, 2022). "Cytokine IFNγ is one of the key factors secreted by immune cells, such as NK cells and T cells, in the tumor microenvironment." (PMID 36525420, 2022). "One-third of these overlapping genes are upregulated in MYC tumor cells and are related to GO terms such as regulated exocytosis, response to cytokines or interferon-gamma, and antigen presentation." (PMID 35318328, 2022). "In conclusion our data show that the HNSCC tumor microenvironment affects NK and T cells, inducing an inhibitory/exhausted phenotype which is reflected in reduced NK cell ability to produce IFNγ after cetuximab engagement." (PMID 36341402, 2022). "Adaptive induced PD-L1 expression is the sequel of the presence of T cells in the TME that are activated by tumor antigens and secrete high IFNγ levels." (PMID 36230402, 2022). "Tumor-infiltrating MPCi-conditioned T cells showed an increase in cells double positive for the effector cytokines IFNγ and TNF." (PMID 35452600, 2022). "During ACT+MS-275 treatment, IFNG expression within the tumor peaked 5 days after treatment, coinciding with peak systemic T cell responses." (PMID 35972798, 2022). "IFNγ and hypoxia are both present in the tumor microenvironment and can each induce PD-L1 expression." (PMID 34268602, 2022). "For example, secreted interferon-γ (IFNγ) can increase the expression of human leukocyte antigen (HLA) class I in tumor cells, thereby enhancing the presentation of tumor antigens to T cells and exerting the killing effect of T cells." (PMID 35222443, 2022). "Data showed so far that for CD4-mediated tumor rejection is necessary antigen presentation by the TAMs and IFNγ signaling." (PMID 35903540, 2022). "The research team confirmed that interferon-γ (IFNγ) generated by tumor-infiltrating cytotoxic T lymphocytes (CTL) can mediate anticancer effects through ferroptosis." (PMID 36684424, 2022).
tumor (continued). "IFN signaling, including type I IFNs (IFNα and IFNβ) and type II IFN (IFNγ), regulates tumor immune responses." (PMID 34385592, 2022). "Since the infiltration of CD8+IFNγ+ T cells into the tumor is key to tumor regression, next, we monitored the infiltration of these cells into TNBC tumor in different groups of PDX mice." (PMID 35053375, 2022). "CD4+ T cells produced the Th1 cytokine IFNγ and the Th2 cytokine IL-4, both of which were required for maximal tumor immunity." (PMID 36159781, 2022). "NGR-TNF and doxorubicin synergism occurs in immunocompetent mice, but not in interferon-γ (IFNγ)– knock-out or nude mice, suggesting that a fully functional immune system and IFNγ are necessary for the overall anti-tumor effects of this combination." (PMID 35890309, 2022). "Ex vivo treatment of primary patient-derived CRC tumor slice cultures with the LY6G6D/CD3 TcE led to IFNγ secretion in LY6G6D positive tumor samples." (PMID 36159851, 2022). "For additional 4 CRC cases (C165, C177, C207 and C215), we stimulated lymphocytes of non-metastatic lymph nodes by autologous tumor cells immediately after making cell suspension and then evaluated tumor-reactive T cells by IFNγ ELISPOT assay." (PMID 35606862, 2022). "It was also found that the in vitro activation of OT-I CD8+ T cells by Hep55.1c-Tet3G-LucOS tumor cells was dependent on the addition of IFNg due to low basal expression of tumor surface H-2Kb (MHC-I)." (PMID 35198900, 2022). "Consistently, Piezo1-/- tumor-bearing mice had more Foxp3+ Treg cells and fewer IFNγ+ TH1 cells in tumor tissue compared with WT control." (PMID 35993548, 2022). "Underexpression of tumor-rejection antigens leads to intrinsic immune resistance and interferon gamma (IFN-γ)-induced high expression of PD-L1 to further induce immune resistance." (PMID 35223804, 2022). "Depletion of T cells or neutralization of interferon-gamma reversed radiation-induced equilibrium leading to tumor regrowth." (PMID 35945555, 2022). "S1P‐treated CD8+ T cells also secreted lower levels of cytotoxic cytokines such as IL‐17, TNF alpha, and IFNγ, which further suggest that S1P is immunosuppressive in the tumor microenvironment." (PMID 35289120, 2022). "Blocking IFNγ decreased PD-L1 upregulation on MDS tumor cells, which is consistent with previous findings on the role of IFNγ in inducing PD-L1 expression in a variety of different cell types, including MDS cells." (PMID 35992887, 2022). "In contrast, Beff cells produce proinflammatory cytokines, including IL-6, IFNγ, and tumor TNFα, to stimulate memory and memory effector CD4+ T cell responses." (PMID 35267563, 2022). "IL-12 also stimulates the production of IFNγ, which induces and maintains higher levels of anti-tumor macrophages." (PMID 36611875, 2022). "IFNγ reduces the number of endothelial cells and induces blood vessel destruction and tumor necrosis." (PMID 36139645, 2022). "In contrast, the immunologically “hot” tumors are termed Infiltrated-inflamed (I–I) tumor immune microenvironment with increased expression of IFNγ." (PMID 35646111, 2022). "IFNγ can activate the cytotoxicity of tumor-specific T cells and NK cells through promoting their release of perforin and granzyme, and IFNγ can heighten antigen presentation to promote inosine-mediated antitumor effects." (PMID 35488243, 2022). "While much of IFNγ’s activity is indirectly cytotoxic, relying on other mechanisms for ultimate destruction of tumor cells, it has a critical role in T cell-mediated tumor cell lysis." (PMID 35163755, 2022). "IFNγ secreted by CD4+ T cells to my induce the expression of interferon-gamma-induced protein 10 (IP-10) and/or monokine induced by IFNγ (Mig) on tumor cells or stroma, leading to inhibition of angiogenesis." (PMID 36159781, 2022). "ICT treated tumours had high expression of these genes, which was further augmented by the addition of tretinoin, with most tumors expressing high levels of IFNγ genes." (PMID 35402250, 2022).
tumor (continued). "Nonetheless, g1 ILCs from the TILN showed reduced IFNγ production upon restimulation, indicating a repressive influence from the tumor." (PMID 36372017, 2022). "GMP NK cells have high IFNγ expression upon cultivation with K562 tumour cells and are highly cytotoxicity toward tumour cell lines in vitro." (PMID 33995362, 2021). "M1 macrophages, which will primarily develop in presence of IFNγ, are acknowledged as potent effector cells for eliminating tumor cells by production of several pro-inflammatory cytokines and activating Th1 cells, thus inhibiting tumor progression." (PMID 33916646, 2021). "Adoptive transfer of tumor-specific IL-4-producing cytotoxic CD8 T cells (Tc2) was also less effective in controlling tumor growth compared to IFNγ-producing CD8 T cells (Tc1)." (PMID 34177932, 2021). "Blocking of IFNG signaling pathway in tumor cells can improve the body’s ability to kill tumor cells and promote the response to ICB." (PMID 34497605, 2021). "CD8+ T cells proliferate and produce effector molecules such as cytotoxic granules (granzyme B, perforin) and proinflammatory cytokines (IFNγ) to mediate tumor cell killing." (PMID 33987104, 2021). "Tumor-free survival required IFNγ-dependent expansion of CD8+ T cells and was related to 4-1BB-mediated differentiation of KLRG1+ effector CD8+ T cells." (PMID 34267616, 2021). "We next evaluated the production of effector cytokine, interferon γ (IFNγ), in immune cells, which play an essential role in anti-tumor immunity." (PMID 33156394, 2021). "An increased infiltration of activated CD44+CD3+CD4+ Th cells into the tumor and an increased IFNγ production were observed in this model." (PMID 34025657, 2021). "IFNγ secreted by Th1 subset of cells can recruit natural killer cells and trigger cytotoxicity of tumor-infiltrating macrophages thus preventing tumor progression and angiogenesis." (PMID 34095125, 2021). "PD1 blockade reinvigorates effector CD8 T cells and these tumor-reactive T cells secrete cytokines, including interferon gamma and tumor necrosis factor alpha (TNFα) and cytolytic enzymes, to kill tumor cells." (PMID 34073253, 2021). "Associated with activation of IFNγ expression, D-Nap-GFFY-T317 enhanced dendritic cell maturation and infiltration into tumors, increased CD3+/CD8+ cells in tumors, and inhibited tumor angiogenesis." (PMID 33456564, 2021). "Tumor gene expression analysis was performed by RNA sequencing in 823 patients from the IMmotion-151 trial, and differential outcomes based on T effector/IFNγ and angiogenesis gene expression signatures were demonstrated." (PMID 34452045, 2021). "In accordance with the previous results, all HER2-CAR T cell populations recognized HER2+ tumor cells and secreted a significant (p < 0.001) amount of IFNγ (MDA-HER2, JIMT-1, N87 panels)." (PMID 34503109, 2021). "We also observed that activated Prkd2-S707A/S711A CD4+ and CD8+ T cells have significantly reduced IFNγ production ex vivo suggesting that T cell PKD function also plays a significant role in tumor growth." (PMID 35046933, 2021). "Early work in murine models found that neutralizing IFNG interferes with tumor rejection in immunocompetent hosts." (PMID 34147519, 2021). "Prolonged IFNG signalling is well known to induce the expression of immune checkpoint molecules such as PD‐L1, thus resulting in tumour immunoevasion." (PMID 34845849, 2021). "Interferon-gamma (IFN-γ) stimulation increases the amount of PD-L1 in tumor exosomes, which suppresses the function of CD8+ T cells and promotes tumor growth." (PMID 34722510, 2021). "The authors went on to show that CAR T cells directed at B7-H3 are capable of crossing the BBB and produce sufficient tumour-killing amounts of IFNγ, IL-2 and TNFα when cocultured with DMG cells." (PMID 34944870, 2021). "In particular, these studies focused on boosting CD4+ T cell-derived secretion of TH1-characteristic tumoricidal cytokines (e.g. IFNγ) as a readout of increased anti-tumour CD4+ responses." (PMID 32457487, 2021).
tumor (continued). "MWA + ICPI treatment was also associated with increased frequencies of CD8 T cells in treated tumours and peripheral blood as well as increased plasma levels of IFNγ." (PMID 34733287, 2021). "IFNγ induces the differentiation, activation, proliferation and survival of tumor specific CD8+ T cells, in part through the induction of regulatory genes including survivin and Ifi202." (PMID 33801234, 2021). "Accumulative evidence has suggested that IFNG activates the anti-tumor immune response through enhancing antigen presentation, T-lymphocyte differentiation and maturation, killing of tumor cells, and suppressing regulatory T cells in various cancers." (PMID 34566988, 2021). "The pro inflammatory cytokine IFNγ is secreted by both the tumor and infiltrating immune cells into the extracellular space acting synergistically to increase HLA expression and enhance antigen presentation." (PMID 33968037, 2021). "The tumor-infiltrated activated CD8+ T cell (IFNγ+CD8+CD3+) population was increased in the combined treatment group." (PMID 33462141, 2021). "Some of our previous findings have shown impairment of the placenta due to the presence of cancer or some tumour factors, such as proinflammatory cytokines interleukin-6 (IL-6), interferon-gamma (IFN-γ), and tumour-necrosis factor (TNFα)." (PMID 33916290, 2021). "Evidence shows that PD-L1 mRNA and protein expression on CAFs derived from NSCLC is upregulated by exogenous supplementation with interferon-gamma (IFN-γ) which has shown to increase exosomal PD-L1 release in tumor cells." (PMID 33628854, 2021). "The IFNγ signaling pathway is thought to be the mechanism behind adaptive resistance, a defense mechanism of tumor cells against the immune system attack by IFNγ secreting CTLs and Th1 cells." (PMID 35087529, 2021). "In fact, IFNγ is highly expressed in cells of the tumor tissues and its neutralization significantly decreased PD-L1+ MDSCs in the TME in vivo." (PMID 33777750, 2021). "We further demonstrated the protection of LXR ligand against tumor growth depends on activation of IFNγ expression, indicating the critical role of cytotoxic effect of macrophage IFNγ on tumor cells." (PMID 33456564, 2021). "The tumor microenvironment is profoundly different from that of healthy tissues; this is also due to the presence of tumor-infiltrating lymphocytes (TILs) that release IFNγ and other inflammatory cytokines." (PMID 34638337, 2021). "In CD8+ T cells expressing MOR and delta-opioid receptor, their ligand, methionine-enkephalin (MENK) causes cell proliferation, activation, increased cytotoxic activity against tumor cells, and increased IFNγ secretion, inducing cytotoxic lymphocyte activity." (PMID 34360996, 2021). "Unfortunately, cancer cells that have been exposed to IFNγ also upregulate molecules such as PD-L1 and indoleamine 2,3 dioxygenase 1 (IDO1) that cause T cell exhaustion and allow tumor progression." (PMID 34829860, 2021). "The same CTLs also showed a significantly higher IFNγ-producing ability against the autologous tumour cells than the wildtype control (p < 0.05)." (PMID 34193879, 2021). "Reducing the IFNγ production by T Helper 1 and enhancing IL-4 secretion via T Helper 2 minimizes anti-tumor immunity and the immune response." (PMID 33472580, 2021). "First, we observed no significant changes in the stroma fraction, cytolytic activity, and PD-1 expression between CNA versus control subgroups in all inquired tumor samples; however, IFNG, GZMA and PD-L1 expression were elevated in mutant (CNA) cancers." (PMID 34598711, 2021). "It is implicated in inhibition of pro-inflammatory mediators production such as IFNγ, antigen presentation, and accumulation and anti-tumor potential of effector T cells." (PMID 35047999, 2021). "In contrast, there were significantly lower values in the high-risk group regarding interferon-gamma (IFNG), MSI score, Merck18, CD274, and tumor-associated macrophage M2 (Mann–Whitney U test P < 0.001)." (PMID 34541005, 2021).
tumor (continued). "Despite its pleiotropic effects, it has been demonstrated that IFNγ-expressing T cells play a dominant role in mediating effective anti-tumor activity." (PMID 33842331, 2021). "Ba. intestinihominis raised chemotherapy of cyclophosphamide through yielding tumor IFNγ T-cell infiltration." (PMID 34589427, 2021). "Specific cells were enriched from splenocytes by their restimulation with tumor antigens in vitro and the selection of activated cells by IFNγ capture assay." (PMID 34576023, 2021). "Previous reports have shown that IFNγ increases the expression of MHC class I molecules in tumor cells, while EGF decreases it." (PMID 33491334, 2021). "Our data indicate that EMT-high tumors lack CTL cytotoxic activity and hence tumor clearance due to limited support of IFNγ, TNFα, and IL2 and abundance of suppressive IL10 and TGFβ cytokines." (PMID 35096592, 2021). "To investigate this, we exposed primary cultures of peritumoral CD90+CD73+ cells (LUSC, n = 8; and LUAD, n = 8, biological replicates) to TNFα and IFNγ, two pro-inflammatory cytokines that feature prominently in inflamed tumours." (PMID 34740105, 2021). "Together with the previous transcription factors, 3D matrices immediately affect also CD73 and IFNγ gene expression with an opposite effect between healthy and tumor conditions." (PMID 34070750, 2021). "We postulate that IFNγR2 induction in Myc-CaP cells makes them more responsive to IFNγ secreted by tumor-infiltrating CTLs." (PMID 33602823, 2021). "In tumors, PD-L1 expression is up-regulated by IFNγ and other cytokines in the tumor microenvironment." (PMID 34240739, 2021). "Our protocol concurrently detecting intracellular CD137, TNF, and IFNγ by flow cytometry identified the majority of the presumed tumor-specific reactive TIL repertoire in the TME." (PMID 34707600, 2021). "Many tumours do not constitutively express MHCII therefore we also examined the tumour therapy in a B16 tumour model where HLA-DP4 is under the control of an IFNγ inducible promoter." (PMID 34858415, 2021). "In contrast, therapy-treated DIO mice exhibited progressive tumor outgrowth and blunted T cell responses, characterized by reduced intratumoral frequencies of IFNγ+ CD4+ and CD8+ T cells." (PMID 34064933, 2021). "Flow cytometric analysis of whole tumours 48 h after treatment with pHIFU + ICI showed increased levels of CD8+ and CD8+IFNγ+ T cells in these tumours relative to control subjects." (PMID 34229458, 2021). "In vivo studies of the diffusion of CD8+ T cell-derived IFNγ suggest that even few intratumoral CD8+ T cells secrete enough IFNγ to reach tumor cells > 800 μm away." (PMID 33801234, 2021). "After tumor immunotherapy, IFNγ released by activated CD8 + T cells downregulates the expression of SLC7A11 and SLC3A2, thereby inhibiting the uptake of cystine in tumor cells and enhancing LPO and ferroptosis." (PMID 34630843, 2021). "On the other hand, the “adaptive immune resistance” situation makes reference to PD-L1 expression by tumor cells in response to IFNγ release by T cells." (PMID 34168976, 2021). "TH1 cells are regarded as tumor-suppressing as they exert various immune response activating functions e.g., they release IFNγ, which promotes recruitment of CTL, M1-macrophages and Natural Killer (NK) cells, and IL-2 which activates CTL." (PMID 34638420, 2021). "We evaluated their anti-tumor efficacy when used as single agents or in combinatorial treatments with anti-CTLA-4 mAbs in in vitro co-cultures of hPBMCs with tumor cells, by measuring tumor cell lysis and IL-2 and IFNγ cytokines secretion by lymphocytes." (PMID 35008285, 2021). "Despite studies demonstrating the pro-tumor activities by Th17 cells, Th17 cells can directly eradicate tumor cells through IFNγ production." (PMID 35056969, 2021). "The stimulation of tumour specific T cells in the local tumour environment releases interferon gamma and this upregulates PD-L1 on the local tumour and other cells." (PMID 34202255, 2021).